RNU6-765P (RNA, U6 small nuclear 765, pseudogene)
Gene: Small nuclear RNA gene on chromosome 9 (38,680,006 to 38,680,104, forward strand). Ensembl gene ENSG00000252725.
Homologues: Orthologues: chimpanzee U6 (97% identical), macaque U6 (90% identical), pig U6 (70% identical). Paralogues in human: RNU6-1011P (85% identical), RNU6-12P (85% identical), RNU6-13P (85% identical), RNU6-31P (85% identical), RNU6-32P (85% identical), RNU6-1 (84% identical), RNU6-15P (84% identical), RNU6-17P (84% identical), RNU6-18P (84% identical), RNU6-19P (84% identical), RNU6-2 (84% identical), RNU6-25P (84% identical), and 1286 more.